RNU6-742P (RNA, U6 small nuclear 742, pseudogene)
Gene: Small nuclear RNA gene on chromosome 18 (57,755,394 to 57,755,500, forward strand). Ensembl gene ENSG00000202159.
Homologues: Orthologues: chimpanzee U6 (100% identical), macaque U6 (90% identical), guinea pig U6 (83% identical). Paralogues in human: RNU6-1209P (92% identical), RNU6-480P (91% identical), RNU6-1175P (90% identical), RNU6-11P (90% identical), RNU6-1309P (90% identical), RNU6-37P (90% identical), RNU6-39P (90% identical), RNU6-774P (90% identical), RNU6-86P (90% identical), RNU6-1145P (89% identical), RNU6-235P (89% identical), RNU6-38P (89% identical), and 1286 more.